TNFSF4 (TNF superfamily member 4)
Diseases named in the same sentence as TNFSF4 in open-access papers (continued):
Sharing a sentence is not in itself a finding about the gene and the disease.
hypothyroidism (2 papers, 2016 to 2019). Abnormally low levels of thyroid hormone. "Interestingly, our study found SNPs in TNFSF4 are associated with hypothyroidism of Hashimoto’s thyroiditis, but not thyroid orbitopathy or GD." (PMID 27556446, 2016).
ischemic stroke (2 papers, 2019 to 2024). A stroke disorder caused by obstruction of blood flow to the brain, due to thrombotic (local blood clot formation) or embolic (due to a blood clot or other material traveling from another site) event. "Therefore, TNFSF4 SNPs can be used as an indicator to define the population with increased susceptibility to ischemic stroke, and to achieve early detection/prevention in order to decrease the morbidity of ischemic stroke." (PMID 30797237, 2019). "However, it is still unclear whether TNFSF4 gene polymorphisms are associated with ischemic stroke in the Han Chinese population." (PMID 30797237, 2019). "Meanwhile, ischemic stroke might be regulated by distinct SNPs of the TNFSF4 gene." (PMID 30797237, 2019). "No study has reported the relationship between TNFSF4 SNPs and LAA or SVD subtypes of ischemic stroke." (PMID 30797237, 2019).
keloid (2 papers, 2020 to 2023). An irregularly shaped, elevated mark on the skin caused by deposits of excessive amounts of collagen during wound healing. "Our results associate keloid tissues with an inflammatory milieu representing multiple T-helper pathways, including the Th2 (e.g. IL-4R, CCL11, TSLP, TNFSF4/OX40L, TNFRSF4/OX40), Th1 (e.g. IFNγ, CXCL10/11), Th17/Th22 (e.g. PI3, CCL20, S100As) axes, as well as the JAK/STAT signaling molecule JAK3." (PMID 33329590, 2020).
mesothelioma (2 papers, 2021 to 2022). A usually malignant and aggressive neoplasm of the mesothelium which is often associated with exposure to asbestos. "OX40 (TNFRSF4) and OX40L (TNFSF4) have been implicated in mesothelioma." (PMID 33952230, 2021).
scleritis (2 papers, 2020 to 2022). Inflammation of the sclera. "This study reveals that a TGT haplotype in TNFAIP3 may be a protective factor for the development of scleritis and that a GT haplotype in TNFSF4 and a CCC haplotype in TNFSF15 may be risk factors for scleritis in Chinese Han." (PMID 33287909, 2020). "In this study, haplotype analysis showed that a TNFAIP3 TGT haplotype, a TNFSF4 GT haplotype, and a TNFSF15 CCC haplotype were significantly associated with scleritis." (PMID 33287909, 2020). "In conclusion, we identified the association of various TNF gene related haplotypes with scleritis in Chinese Han, including TGT in TNFAIP3, GT in TNFSF4, and CCC in TNFSF15." (PMID 33287909, 2020). "We also found a higher frequency of the TNFSF4 GT haplotype in scleritis patients." (PMID 33287909, 2020). "In addition, a study on the genotypes of TNF-α-related genes in Chinese Han patients with scleritis found that specific haplotypes in TNFAIP3 (TNF-α-induced protein 3), TNFSF4 (TNF-αreceptor superfamily member 4), and TNFSF15 might be the risk or protective factors of scleritis in Chinese Han." (PMID 36431163, 2022).
silicosis (2 papers, 2021 to 2024). Silicosis is a respiratory disease caused by breathing in (inhaling) silica dust. "Miaoet al.30 also found that TNFligand superfamily 4 isoform X1 (TNFSF4), IFN-β precursor, IL-6, atypicalchemokine 2 receptor, and mutant IL-17F were all upregulated in exposed patients,both with and without silicosis." (PMID 39606764, 2024).
thymoma (2 papers, 2022). A neoplasm arising from the epithelial cells of the thymus. "Strikingly, in THCA and THYM (thymoma), NEIL3 was significantly associated with more than 20 immune checkpoint genes, such as CD86, ICOS, TNFSF4, and CD48, implying its role in regulating the tumor immune microenvironment." (PMID 36612106, 2022).
autoimmune uveitis (1 paper, 2017). An autoimmune form of uveitis (disease). "Additionally, previous studies have indicated that blocking TNFSF4 can inhibit ocular inflammation in a mouse model of experimental autoimmune uveitis, and activation of the TNFSF4 receptor augments Th17 cell function and thereby contributes to ocular inflammation." (PMID 29285231, 2017).
bacterial meningitis (1 paper, 2025). Inflammation of the membranes surrounding the brain and spinal cord due to a bacterial infection. "This study delineates the oar-miR-125b/TNFSF4/NF-κB regulatory axis, deepening our molecular comprehension of bacterial meningitis pathogenesis and underscoring its considerable translational relevance." (PMID 41471849, 2025). "This study establishes the oar-miR-125b–TNFSF4–NF-κB axis as playing a critical role in bacterial meningitis pathogenesis." (PMID 41471849, 2025). "Significantly, this study is the first to link the oar-miR-125b-TNFSF4-NF-κB axis to tight junction regulation, revealing a complete signaling pathway through which inflammatory responses induce blood–brain barrier dysfunction in bacterial meningitis." (PMID 41471849, 2025). "Collectively, our results demonstrate that oar-miR-125b serves as a key anti-inflammatory regulator in bacterial meningitis by targeting TNFSF4 and constraining NF-κB signaling, highlighting its potential as a therapeutic target for attenuating neuroinflammation in meningitis." (PMID 41471849, 2025).
cerebral infarction (1 paper, 2020). An ischemic condition of the brain, producing a persistent focal neurological deficit in the area of distribution of the cerebral arteries. "Furthermore, subgroup analysis based on disease type showed that TNFSF4 rs3861950 T > C had a robust correlation with increased risk of cerebral infarction (CI) in the allelic model, dominant model, heterozygous model, and homozygous model." (PMID 33329013, 2020).
end-stage renal disease (1 paper, 2022). "Investigating the genetics contribution to the development of chronic damage, we found a significant association between rs2205960 SNP of TNFSF4, the development of irreversible renal damage and two specific items of this domain [end-stage renal disease and estimated GFR < 50%]." (PMID 35743441, 2022).
Enterococcus faecalis infection (1 paper, 2025). A bacterial infection induced by Enterococcus faecalis which is the most prevalent species (along with Enterococcus faecium) cultured from humans, accounting for more than 90% of clinical isolates. "This discovery suggests that monitoring oar-miR-125b levels in blood or CSF, along with TNFSF4 concentrations, could serve as a novel, minimally invasive diagnostic approach for identifying patients at high risk of CNS complications caused by Enterococcus faecalis infection." (PMID 41471849, 2025).
fungal infection (1 paper, 2020). "However, although we have provided some insights about the functional role of the TNFSF4 and MAPKAPK2 polymorphisms in determining the risk of IA, we believe that additional studies are still warranted to identify the exact mechanisms by which these loci modulate the risk of fungal infection." (PMID 33374839, 2020).
Hypertension (1 paper, 2025). The presence of chronic increased pressure in the systemic arterial system. "Of particular interest are the SNPs within the NOS3 (endothelial nitric oxide synthase), F5 (Leiden factor), TNFSF4 (cytokine pathway), and CDKN2B-AS1 (cell cycle regulation) genes, which may play a key role in the development of vascular dysfunction and hypertension in this pathology." (PMID 40507612, 2025).
meningitis (1 paper, 2025). A disorder characterized by acute inflammation of the meninges of the brain and/or spinal cord. "In this study, using a lamb model of Enterococcus faecalis-induced meningitis, we observed significant downregulation of oar-miR-125b, which inversely correlated with its newly identified target, Tumor Necrosis Factor Superfamily Member 4 (TNFSF4)." (PMID 41471849, 2025).
neuromyelitis optica spectrum disorders (1 paper, 2020). "In earlier reports, the GT haplotype of the TNFSF4 gene (order of SNPs: rs844648, rs704840) played a protective role in neuromyelitis optica spectrum disorders in Chinese." (PMID 33287909, 2020).
parasitic infection (1 paper, 2020). "In addition, another study showed that miR-125a, which is involved in determining the commitment and immunosuppressive capacity of Treg cells, was highly expressed in a model of parasitic infection and that it mediated its action through the regulation of both TNFSF4 and MAPKAPK2 genes." (PMID 33374839, 2020).
thyroid-associated ophthalmopathy (1 paper, 2016). "However, our results cannot add the TNFSF4 gene to the list of the predisposition of thyroid-associated ophthalmopathy (TAO)." (PMID 27556446, 2016).
tumor (250 papers, 2011 to 2026). "In the subgroup of patients with low lymphocyte infiltration, the low expression of TNFSF4mRNA was also associated with poor prognosis, suggesting that tumor TNFSF4 was related to prognosis." (PMID 35003069, 2021). "CXCL9 was also induced in the metronomic CPA-treated tumor cells in association with other extracellular immune activators: TNFSF4, MICB, interleukins IL12, IL15, IL23, and IL17RB, and interferon response genes." (PMID 25952672, 2015). "It is suggested that TNFSF4 is associated with tumor prognosis." (PMID 37858131, 2023). "A study in this area transformed tumor cells into aAPCs by infecting them with a herpes simplex virus 1-based oncolytic virus encoding IL-12 and TNF superfamily member 4 (TNFSF4 or OX40L) to induce stimulatory signals for the maximum activation of effector T cells." (PMID 36010836, 2022). "Expression of four genes decreased after CaPa, TNFSF18, coding for GITRL, HMGB1, TNFSF4, coding for OX-40 L and HLA-A, all involved in the positive regulation of anti-tumor immune response." (PMID 38581044, 2024). "There are some literature reports focusing on the role of KIT and TNFSF4 in the anti-tumor activity of NK cells." (PMID 39201666, 2024). "A recent study has indicated that YTHDF1 is highly expressed in BRCA tumor tissue, creating a “cold” tumor microenvironment by suppressing the release of pro-inflammatory cytokines Ccl7, Il-17rb, Sell, Cxcl2, and Tnfsf4 in BRCA cells." (PMID 38202722, 2023). "SLC7A11 expression was positively associated with the expression of immune checkpoint genes (NRP1, TNFSF4, TNFRSF9, and CD276) and tumour mutation burden." (PMID 37919768, 2023). "Expression analysis revealed that HPV integration disrupted gene expression, but the upregulation of CD274, PDCD1LG2, FOXA1, and TNFSF4 provided opportunities for tumor immunotherapy." (PMID 35392231, 2022). "In order to corroborate the observed expression of TNFSF4 on B-ALL tumor cells, we examined the expression of the gene in both B-ALL cell lines." (PMID 33648458, 2021). "Both DCs and TAMs from the tumor exhibit some expression of TNFSF4, encoding OX40 Ligand (OX40L), suggesting the increased frequency of TNFRSF4 activation could be due to interactions with these cell types." (PMID 39811671, 2025). "The positive correlation between PYGB and TNFSF4 (also known as OX40L), a co-stimulatory molecule that enhances T-cell activation and survival, suggested its potential role in modulating T-cell responses and promoting anti-tumor immunity." (PMID 40458414, 2025). "Subsequently, all factors identified from the univariate analysis were included in the multivariate analysis: age, PDCD1/CD27 ratio, PDCD1/TNFSF4 ratio, IDO1/TMIGD2 ratio, IDO1/TNFSF4 ratio, neoadjuvant treatment, initial weight of tumor, ER status, PR status, HER2 status, and TNM stage." (PMID 40061889, 2025). "In tumor immunology, the TNFSF4/OX40L axis displays dual functions." (PMID 41471849, 2025). "TNFSF4 is closely related to the induction of anti-tumor immunity." (PMID 37510310, 2023). "Additionally, the analysis of the CGGA and TCGA databases also showed that CDCA7 was closely related to several tumor-related suppressors, including CD80, CD276, CD28, PDCD1LG2, and TNFSF4, which contribute to tumor development via multiple mechanisms." (PMID 37510310, 2023). "TNFSF4 can promote the chemotherapy resistance of cancer cells by inhibiting tumor cell apoptosis." (PMID 37511932, 2023). "According to our Transwell migration assay, it is assumed that T cells expressing TNFSF4 in the TME of GBM might induce NK cell migration into the tumor, resulting in a better therapeutic effect of our AKC treatment." (PMID 36694264, 2023). "At the same time, we found that ALDOA may be co-expressed with TNFSF4 to regulate tumor immune infiltration." (PMID 35804089, 2022).
tumor (continued). "Our results showed that ALDOA regulates the co-expression of TNFSF4 in a variety of tumors, which may have a certain correlation with the tumor’s immune microenvironment and prognosis." (PMID 35804089, 2022). "The rest genes, CD46, CXCL6, GPI, ITGB1, PLA2G6 and TNFSF4, were revealed for the negative association with tumor suppression." (PMID 35832540, 2022). "Metronomic CPA treatment also induced a core set of death-related genes that may be important for innate and/or adaptive immune activation by damaged tumor cells, including Sp110, Mx1, Mx2, Ebi3, Eomes, Tnfsf4, Gdf15, Ddx58, and Dhx58." (PMID 25952672, 2015). "Notably, NCAPG2 methylation showed a positive correlation with TNFSF4 (r = 0.347, p = 0.0386).Therefore, NCAPG2 may linked to regulate tumor immunity." (PMID 40447854, 2025). "To validate whether expression of the three candidate genes (TNFSF4, TNFRSF18, and IL12RB2) in the tumor microenvironment is implicated in NK cell migration toward cancer cells, we conducted a Transwell migration assay using GBM U87MG cells, T cells, and NK cells derived from PBMCs." (PMID 36694264, 2023). "We identified 1,758 HB-specific and 1,803 non-tumor-specific TAD boundaries, containing 81 and 108 DEGs, respectively, such as TDGF1, TNFSF4, and REG3A." (PMID 41462308, 2025). "In mouse models, the targeted delivery of TNFSF4 increased CD8 T cells and NK cells to provide local anti-tumor immunity." (PMID 37511932, 2023). "TNFSF4, also known as OX-40L, is a member of the TNF superfamily, which provides signals for CD4 T cell responses and plays an important role in tumor immunotherapy." (PMID 35804089, 2022). "Increased levels of GITR, TNFSF4 (OX40L), and 4-1BB suggest activation, while increased MKI67 expression identifies cluster 4 as the most proliferative cluster in the tumor." (PMID 33602930, 2021). "For example, when exposed to thymic stromal lymphoprotein from tumor or thymus, or TNF-α, DC express OX40 ligand, which is a member of the TNF superfamily (TNFSF4)." (PMID 33986746, 2021). "Results showed that interactions participating in immune activation and anti-tumor response, such as, CXCL9-CXCR3, CXCL9-DPP4, XCL2-XCR1, and TNFSF4-TNFRSF4 upregulated in tumors, partly due to the continuous stimulation of tumor antigens." (PMID 33298893, 2020). "The TNFR superfamily proteins are expressed by antigen-presenting cells (APC) or tumor cells, including TNFSF4 (OX40L), TNFRSF5 (CD40), TNFSF7 (CD70), TNFSF9 (CD137L), TNFRSF14 (HVEM), and TNFSF18 (GITRL)." (PMID 30609841, 2019). "In addition, magnesium homeostasis is also closely related to the expression of immune activation genes in tumor microenvironment, such as TNFRSF13C, BTNL2, TNFSF4 and so on, thus promoting anti-tumor immune response." (PMID 41174507, 2025). "Using OX40LHu-CD4 (Tnfsf4)-reporter mice, we confirmed that some tumour CCR7+ DCs express OX40L, but it was not expressed by tumour cDCs or CCR7+ DCs in the dLN." (PMID 38267413, 2024). "Importantly, we identified several lymphocyte activation ligands that were significantly upregulated on Ccr7_DC.2 versus other tumour CCR7+ DC states and Kaede-red dLN CCR7+ DCs, such as Il12b, Tnfsf4, Tnfsf9, Cd70 and Pvr." (PMID 38267413, 2024). "When T cells encounter antigens presented by pathogens or tumor cells, they become activated; OX40 is upregulated on these T cells and binds to its ligand [OX40L (CD134L; TNFSF4; CD252)], which is typically found on antigen-presenting cells, including but not limited to dendritic and B cells." (PMID 38526805, 2024). "In conclusion, we identified TNFRSF18, TNFSF4, and IL12RB2 as biomarkers that predict response to NK cell therapeutics by studying the tumor immune microenvironment using NanoString and qRT-PCR analyses in patients with recurrent GBM who received activated NK cell treatment." (PMID 36694264, 2023).
tumor (continued). "TNFSF4 was significantly upregulated in lung fibroblasts exposed to stress, and there was a negative correlation between TNFSF4 and tumor shrinkage after treatment with chemotherapeutic agents." (PMID 36797708, 2023). "We identified TNFRSF18, TNFSF4, and IL12RB2 as biomarkers that predict response to NK cell therapeutics in recurrent GBM, which might provide a new treatment strategy for this highly aggressive tumor." (PMID 36694264, 2023). "Our results demonstrated that the mRNA expressions of IL-5, IL-1A, CXCL10, TNFSF4 and INHBE were significantly altered when regulating C1QTNF6, which suggested the essential implications of the cytokine-cytokine receptor interaction pathway in the process of C1QTNF6 regulating tumor progression." (PMID 35879698, 2022). "Proteins OX-40 ligand (OX-40 L/TNFSF4/CD134L/CD252) and 4-1BB ligand (4-1BBL/TNFSF9/CD137L) regulate effector cytotoxic T-cell (CTL) activity while programmed death ligand-1 (PD-L1) exhibits immunosuppressive effects, allowing the tumor to escape immune destruction." (PMID 30064416, 2018).